TNF (tumor necrosis factor)
Diseases named in the same sentence as TNF in open-access papers (continued):
Sharing a sentence is not in itself a finding about the gene and the disease.
influenza (447 papers, 2007 to 2026). An acute viral infection of the respiratory tract, occurring in isolated cases, in epidemics, or in pandemics; it is caused by serologically different strains of viruses (influenzaviruses) designated A, B, and C, has a 3-day incubation period, and usually lasts for 3 to 10 days. "TNF production by macrophages has also been associated with increased viral control after influenza infection, highlighting the need to balance immune activation for viral clearance with that of control for overshooting inflammation." (PMID 40263611, 2025). "Increased HbA1c levels correlate with reduced TNF-α production by CD8+ T cells in response to influenza stimulation, linking this with the increased risk of severe influenza in patients with diabetes." (PMID 41511331, 2025). "TNF-α blockade reduces lung injury but compromises CD8+ T cell recruitment, while human data associate high TNF-α levels with both severe disease and recovery, suggesting context-specific roles in influenza infections." (PMID 40872830, 2025). "Cytokine, chemokine, and interferon levels are altered during influenza infection in IL‐6 deficient mice, including increased TGFβ by day 6 post‐infection and increased TNFα, IFNα, and CCL2 by day 7 post‐infection." (PMID 40420617, 2025). "In patients with IBD, the use of systemic steroids and anti-TNF inhibitors is associated with a higher risk of pneumococcal and influenza infections." (PMID 40145951, 2025). "Increased inflammatory monocytes, increased TNFα+ inflammatory monocytes, and decreased neutrophils have been observed in the airway compartment in IL‐6 deficient mice during influenza infection." (PMID 40420617, 2025). "Prototypical cytokines and chemokines associated with influenza, including interferons (IFNs), tumor necrosis factor (TNF) α, interleukin (IL)−6, and CCL2 were upregulated throughout infection in the lungs but not the spleens of IAV-infected dams." (PMID 38190129, 2024). "The TOLL receptor pathway, which triggers inflammatory damage during viral cytopathogenesis, is often thought to be highly associated with increased influenza morbidity and significant changes in TNF-α, IL-6 and iNOS during Toll receptor pathway activation." (PMID 38426086, 2024). "Apart from analyzing antiviral activity, the authors also studied the levels of NF-κB and proinflammatory cytokines, such as TNF-α, IL-1β, and IL-6, generally associated with influenza infection, which were reduced by the treatment with the HA2 dendrimer." (PMID 38140131, 2023). "Interleukin‐6 (IL‐6), monocyte chemoattractant protein‐1 (MCP‐1) and tumor necrosis factor (TNF) are pro‐inflammatory cytokines commonly associated with influenza‐induced cytokine storms." (PMID 36969366, 2023). "The TNFα blockade has been associated with reduced antibody responses to other vaccines, such as influenza and pneumococcal." (PMID 35893835, 2022). "Anti tumour necrosis factor (anti-TNF) drugs increase the risk of serious respiratory infection and impair protective immunity following pneumococcal and influenza vaccination." (PMID 35296643, 2022). "The GO enrichment analysis revealed 452 transcripts associated with KEGG pathways for influenza and both the TNF and nuclear factor κB (NF-κB) signaling pathways." (PMID 35562916, 2022). "Previous studies have shown influenza infection can cause the production of TNF-α, IL-1β, IFN-γ, and IL-6." (PMID 34552653, 2021). "The use of anti-TNFα agents and immunomodulators, especially when used combined, is associated with a lower serological response to influenza vaccination in both children and adults with IBD." (PMID 32824111, 2020). "While the role of elevated TNF‐alpha in influenza pathogenesis has been well‐studied, the association between an overactive IL‐2 response and morbidity in influenza infection is less clear." (PMID 30156030, 2019).
influenza (continued). "In lung homogenates, influenza by itself caused mildly elevated levels of TNF-α, IL-1β, IL-6, and IL-10 at 4 days post-infection and to a lesser extent at 10 days after infection." (PMID 29978355, 2018). "Our study also contrasted with previous studies that had demonstrated that the loss of TNF increased the severity of influenza infection, as assessed by weight loss, and increased CD8+ T cell response magnitude in the lung." (PMID 28886201, 2017). "With regard to its proinflammatory role, TNF has been linked to increased morbidity upon influenza infection, possibly through exacerbation of lung inflammation by promoting recruitment of immune cells." (PMID 28886201, 2017). "Similar MBL deficiencies lead to increased infection by influenza and exaggerated macrophage activation and increases in inflammatory cytokines, such as IL-1β and TNFα." (PMID 28619036, 2017). "Severe influenza causes marked increases in the levels of proinflammatory cytokines, such as tumor necrosis factor (TNF)-α, interleukin (IL)-6, and IL-1β, coined the cytokine storm." (PMID 24865588, 2014). "Their study showed that TNF-α was up-regulated in the lung after influenza infection and TNF-α deficiency led not only to a greater extent of illness but also to heightened lung immunopathology and tissue remodeling." (PMID 24725777, 2014). "This was presumably due to increased production of TNF-α by influenza-specific CD8+ T cells as NKG2A-deficiency resulted in enhanced production of TNF-α and IFN-γ by these cells in vitro." (PMID 25251060, 2014). "In particular, levels of cytokines IL-6 and TNF-α were reported to be positively correlated with influenza associated lethality." (PMID 24124485, 2013). "Pro-inflammatory cytokines, including TNF-α, interleukin (IL)-1β, and IL-6 have been implicated in the loss of appetite and weight in influenza infection, chronic inflammatory disorders and cancer." (PMID 22536437, 2012). "In contrast, in the case of high-dose influenza, smoke exposure was associated with heightened IL-6 and TNFα responses." (PMID 20920950, 2011). "The TNF-α expression level was also assessed given that it has been previously implicated in influenza immunopathology." (PMID 21304882, 2011). "We thus asked if the decreased effector response to influenza vaccine in RA patients treated with anti-TNF is associated with the observed decrease in memory B cell and serum antibody on a per-patient basis." (PMID 22177419, 2011). "The treatment induced expression of the inflammatory cytokines IL-6 and TNF in bronchoalveolar lavage fluid 8- and 40-fold greater, respectively, than that caused by lethal influenza infection." (PMID 19137067, 2009). "In addition, high serum levels of the pro-inflammatory cytokine, tumor necrosis factor α, has been negatively associated with influenza-specific haemagglutination inhibition titers in older humans following influenza virus vaccination." (PMID 35903142, 2022). "A study conducted on 246 patients infected with A/H1N1pdm09 virus in India, suggested that SNPs in the IL-10 and TNF-α genes might be associated with disease severity in influenza A/H1N1pdm09-infected patients." (PMID 33766078, 2021). "Interstitial macrophages are known to secrete IL-1, IL-6, and TNF-α and thus, could play a pathogenic role during S. pneumoniae-influenza superinfection." (PMID 33690728, 2021). "TNF blockers cause the most impaired serological response to the trivalent influenza vaccine." (PMID 34136315, 2021). "In our network, GO and KEGG results yielded two compounds (beta-sitosterol (BS) and pelargonidin (PG)), targets (PTGS1 (COX-1) and PTGS2 (COX-2)), and pathways (nitric oxide, TNF) were involved in the inhibitory effects of FT on influenza-associated inflammation." (PMID 32854331, 2020).
influenza (continued). "Patients with influenza-associated acute encephalopathy/encephalitis exhibited neurological symptoms like seizure, altered arousal, and abnormal behaviors, which were associated with increased concentrations of IL-1β, IL-6, and TNF-α in serum and CSF." (PMID 32850927, 2020). "Moreover, TNF-α (top) and IL-6 (bottom) mRNA expression in unstimulated B cells are negatively associated with the in vivo influenza vaccine response (B) and with the in vitro AID mRNA expression (C)." (PMID 32180773, 2020). "In a systematic review evaluating the efficacy of vaccines in patients using immunosuppressant therapy, it was noted that the use of TNF-α antagonists in combination with methotrexate was associated with a reduction of immunogenicity of influenza and pneumococcal vaccines." (PMID 30871593, 2019). "In addition, the induction of AQP4 expression and edema formation has been well studied in animals with influenza-associated encephalopathy induced by proinflammatory cytokines, including IL-1, IL-6 and TNF-α in cultured astrocytes." (PMID 29216295, 2017). "This dysregulation of TNF-α and IL-6 vs. IL-10 response to influenza vaccination has been linked to the downregulation of the expression of the costimulatory molecules CD80 and CD86 by activated monocytes as a predictor of the antibody response to influenza vaccination." (PMID 28769922, 2017). "High levels of serum TNF-α in the elderly was associated with impaired influenza vaccine response." (PMID 26930208, 2016). "Interestingly, our group has previously shown in humans that CD11bhi-expressing monocytes are highly proinflammatory (production of TNF-α and IL-6 following LPS stimulation) compared with CD11blo, and they negatively associate with influenza vaccine–induced antibody titers in HIV+ individuals." (PMID 34491910, 2021). "The elevated levels of proinflammatory cytokines (TNFα, IL-1β and IL-10) during influenza infection have also been primarily associated with increased lung pathology and worse outcomes, but it is uncertain whether some of these cytokines could also be protective during seasonal influenza infection." (PMID 29545521, 2018). "One of the earliest immune responses to influenza infection is to produce pro-inflammatory cytokines such as IL-6 and TNF-α alongside interferons such as IFN-α and IFN-β, which facilitate the recruitment of immune cells to defeat the infection." (PMID 41602762, 2026). "Viral invasion can result in edema and cellular infiltration of the AV node, leading to conduction disturbances, whereas a severe influenza infection leads to a cytokine storm, with elevated levels of tumor necrosis factor (TNF-α), IL-1, and IL-6." (PMID 40585744, 2025). "Higher TNFα and IL-6 levels in influenza patients have been shown to correlate with severe disease or fatal outcome." (PMID 40333697, 2025). "It is now clearly known that severe cytokine storms, with elevated levels of IFNs and TNF-α, have been observed in patients hospitalized due to influenza infection." (PMID 41511331, 2025). "This likely extends to other antigens, as impaired humoral responses in patients with IBD treated with anti-TNF have also been demonstrated in the context of influenza vaccination." (PMID 40728886, 2025). "We evaluated serum concentrations of seven cytokines (IL-2, IL-4, IL-6, IL-10, TNFα, IFNγ, and IL-17a) as potential biomarkers for influenza severity in pregnant women." (PMID 40558593, 2025). "Elevated levels of pro-inflammatory cytokines, especially IL-6 and tumor necrosis factor-alpha (TNF-α), are consistently observed in severe cases of influenza." (PMID 41583233, 2025). "Inflammatory cytokines such as TNF-α and IL-6, released post-influenza infection, can further enhance bacterial adhesion and invasion." (PMID 40572089, 2025). "Increased level of IL-6, IL-1β, TNFα, and IFN-β in response to influenza can damage the placenta and cause intrauterine fetal growth impairments." (PMID 41567998, 2025).
influenza (continued). "Centrum germinativum response is essential for memory B cell formation, and the anti-TNFα therapy blocked this response, thereby reducing peripheral memory B-cell numbers and consequently reducing the response to influenza vaccination detectable." (PMID 40281592, 2025). "BCG vaccination influences the increase in TNF-α and IL-6 production following influenza vaccination." (PMID 40718526, 2025). "We conclude that ACh-producing B cells directly modulate TNF production by lung IMs early after influenza infection." (PMID 40263611, 2025). "In influenza and staphylococcal sepsis, cytokines such as IL-6 and TNF-α promote tissue factor expression and suppress anticoagulant pathways (e.g., protein C, antithrombin), leading to microthrombi and consumption of clotting factors." (PMID 40564724, 2025). "BCG vaccination influences the increase in TNF-α and IL-6 production induced by the influenza vaccination." (PMID 40718526, 2025). "In diabetic patients, hyperglycemia impairs CD8+ T cell responses to influenza virus infection, as increased HbA1c levels correlate with reduced TNF-α production by these cells in response to influenza stimulation." (PMID 41511331, 2025). "During singular influenza infection, increased TNFα and increased TNFα production by monocytes was observed in the airways of IL‐6 deficient mice, whereas we saw no changes during IAPA." (PMID 40420617, 2025). "The current evidence supports the anti-influenza and anti-inflammatory properties of alkaloids, but their relationship with inflammatory mediators such as IL-6 and TNF-α needs further clarification." (PMID 40076449, 2025). "Early secretion of Th17 (IL-8, IL-9, IL-17, IL-6) and Th1 cytokines (TNF-α, IL-15, IL-12p70) were detected in severe influenza patients, which were involved in cell-mediated immunity, may be associated with pathogenesis and autoimmune diseases induced by influenza." (PMID 40248710, 2025). "Newly identified triggers included COVID-19 infection, SARS-CoV-2 and influenza vaccines, aluminum- and gelatin-containing pediatric vaccines, and biologic therapies such as ustekinumab and tumor necrosis factor-alpha (TNF-α) inhibitors." (PMID 40488888, 2025). "Our results showed that increasing HbA1c correlated with a reduction in TNF-α production by CD8+ T cells in response to influenza stimulation in a TCR-specific manner." (PMID 38214784, 2024). "In this study, the mice that were infected with influenza and were orally administered the mixed probiotics showed significant reductions in IL-6 and TNF-α levels, suggesting a potential alleviation of influenza-induced inflammatory storms." (PMID 39410114, 2024). "For instance, tumor necrosis factor receptor 1 (TNFR1) deficient mice are less susceptible to H5N1 virus infection, and treatment with anti-TNF antibodies reduces the severity of illness under influenza or respiratory syncytial virus infection." (PMID 38470034, 2024). "Chills inchildren with Influenza are attributable to higher inflammatory response characterized by higher levels of IL-1 and TNF α." (PMID 38712005, 2024). "Most data is available on anti-TNF-α therapy for rheumatoid arthritis, and with regard to the type of vaccination, it is the flu vaccine (influenza vaccine)." (PMID 39600395, 2024). "OM-85 protected mice against nebulized influenza viral infection by increasing IL-6 and tumor necrosis factor α (TNF-α) expression in bronchoalveolar lavage fluid compared to fatal influenza infection." (PMID 38962577, 2024). "During influenza infection, the host’s immune system releases a large amount of cytokines (such as TNF-α, IL-6, and IL-8) and chemokines, among other inflammatory mediators." (PMID 39410114, 2024). "The secretion of inflammatory cytokines such as TNF-α, IL-1β, and IL-6 post influenza infection also promotes bacterial adhesion and invasion." (PMID 39065060, 2024).
influenza (continued). "Four studies were able to show that the antibody response to influenza vaccination is attenuated under anti-TNF-α therapy, whereas three studies were able to demonstrate a normal vaccination response." (PMID 39600395, 2024). "Etanercept, which is endowed with anti-TNF-α activity, controlled severe influenza, impairing proinflammatory programmed cell death in IAV-infected mice." (PMID 36875528, 2023). "As expected, blocking IFN-γ and TNF activity in aged influenza-infected mice ameliorated fibrotic sequelae when compared to isotype controls." (PMID 38077031, 2023). "We thus, decided to test the impact that taming TNF levels during influenza infection would have in the generation of antigen-specific lung CD8+ TRM." (PMID 37468506, 2023). "During inflammation, influenza vaccination leads to reduced levels of proinflammatory cytokine (IL-6, IL-8 and TNF-α) and an increase in IL-10 levels." (PMID 37766096, 2023). "The superinfected lungs had significantly elevated levels of IL-6, TNFα, and IFNβ during the early stages of influenza infection, but their levels dropped if the fungal challenge occurred at later stages of influenza infection." (PMID 37681974, 2023). "The data indicated that nasal-spraying Bacillus spores significantly decreased IL-6, IL-8, and TNF-α cytokine overreacted production, and to some extend increase nasal IgA level in immunological responses to influenza infection." (PMID 37684332, 2023). "TNF-α is a multifunctional inflammatory cytokine that plays a key role in the development of severe influenza." (PMID 35669119, 2022). "One probable mechanism underlying the effect of MEDI3622 on lung inflammation is reduction of soluble TNF-α, as is the case in an influenza pneumonia model." (PMID 35757773, 2022). "QQXD can reduce the expression of IL-1α, IL-4, IL12(P70), and TNF-α inflammatory factors in influenza mice, and prevent the excessive inflammatory reaction from aggravating lung injury." (PMID 36313993, 2022). "A diminished antibody response to seasonal influenza vaccine in patients receiving TNF inhibitors has been reported in several studies; however, some other studies have reported a normal humoral response." (PMID 35214755, 2022). "In influenza-induced tissue damage, IL-1β and TNF-α are induced to be expressed in type II alveolar epithelial cells and contribute to alveolar regeneration by acting directly on alveolar epithelial cells via surface receptors and NF-κB signaling pathways." (PMID 36052144, 2022). "Lung homogenates were evaluated by multiplex ELISA (Quansys) to quantify several cytokines (TNFα, IFNγ, IL-1α, IL-1β and IL-6) and chemokines (MCP-1, MIP-1α and RANTES) implicated in influenza-mediated acute lung injury 33,34." (PMID 35410323, 2022). "Infection with influenza leads to the activation of inflammatory cells and an increase in pro-inflammatory cytokines such as IL-1, IL-6, and TNF-α." (PMID 36560418, 2022). "An experimental study in a severe influenza model in mice showed the high potential of DADA in reducing the cytokine storm including IL-2, IL-6, IFN-α, TNF, and IFN-γ, in addition to its role in restoring the down-regulated PDH activity caused by influenza." (PMID 35355991, 2022). "For example, Lianhuaqingwen Capsule (LH-C) has proven effective against influenza and reduced the pro-inflammatory cytokines (IL-6 and TNF-α) in the lungs of mice." (PMID 35123452, 2022). "Canonical inflammatory cytokines like TNF-α, IL-1β and interferons, are secreted by virus-infected epithelial and stromal cells during various stages of influenza infection." (PMID 36895258, 2022). "Tumor necrosis factor alpha (TNF-α) is a multifunctional cytokine that has a potent antiviral role against influenza, hepatitis C, African swine fever virus, and RV." (PMID 36297136, 2022).